CCL17 (C-C motif chemokine ligand 17)
Diseases named in the same sentence as CCL17 in open-access papers (continued):
Sharing a sentence is not in itself a finding about the gene and the disease.
tumor (continued). "Substantial reductions in suppressive cytokines, including CCL2, CCL17, CCL22 and IL-10, were also noted and were associated with reduced CD4+ CD25+ Foxp3+ Treg recruitment in the tumour." (PMID 33513866, 2021). "To gain mechanistic insights regarding tumor immunity in AD, we utilized CCL17 transgenic (TG) mice overexpressing CCL17, which is a key chemokine in AD." (PMID 33670758, 2021). "Ccl2 and Ccl7 (also known as monocyte chemoattractant protein 1 and 3, respectively) play a critical role in the recruitment of monocytes and neutrophils to the inflamed or tumor tissue, while Ccl17 attracts regulatory T cells." (PMID 34504786, 2021). "Here we show that LFPRLR knockdown in the highly metastatic, immunocompetent 4T1 model prolonged survival and reduced recruitment of T regulatory cells (Tregs) to the tumor through effects on the production of CCL17." (PMID 34375938, 2021). "Consistent with this, when the patients were subdivided into 4 groups based on the Knosp classification system, CCL17 expression was higher in high-grade PA tissues than in low-grade tumor tissues as assessed by qPCR and immunofluorescence staining." (PMID 33664865, 2021). "Strong positive-correlations (r > 0.5, p < 0.05) were observed between the expression of CXCL10 and CCL5 and CD8+ T cell abundance in tumours, while CCL17 and CCL22 were negatively correlated (r < −0.5, p < 0.05) with CD8+ T cell infiltration." (PMID 33925140, 2021). "CCR4 ligands CCL22 and CCL17, each involved in Treg recruitment into the tumour microenvironment (TME), were comparatively decreased in mice treated with sitagliptin and were consistent with the observed decrease in Treg abundance." (PMID 33513866, 2021). "Clinical data showed that CCL17 expression is positively correlated with tumor invasion in PA patients." (PMID 33664865, 2021). "Moreover, we illustrated that higher CCL17 expression in human PAs predicts larger tumor size, greater invasion, and more susceptibility to postoperative recurrence than PAs with lower CCL17 expression, thereby emphasizing the clinical value of CCL17 as a prognostic marker." (PMID 33664865, 2021). "It has been reported that CCL17 positively regulates tumor development in hepatocellular and gastric carcinomas." (PMID 33670758, 2021). "Subsequently, these TAMs then secrete CCL17 to enhance tumor invasion via the CCL17/CCR4/mTORC1 axis." (PMID 33664865, 2021). "In the TME, the presence of CAFs and their secretion of chemokines and cytokines such as CCL2, CCL5, CCL17, IL-1, IL-6, IL-13, and IL-26 can favor a tumor-promoting Th2 and Th17 immune response, at the expense of tumor-protective Th1 responses." (PMID 34663337, 2021). "Through a variety of analyses, we were able to conclude that LFPRLR knockdown decreased production of the Treg chemoattractant, CCL17, by tumor parenchyma." (PMID 34375938, 2021). "In HCC, tumor-infiltrating Tregs are recruited to the neoplastic site following enhanced secretion of the chemokines CCL17 and CCL2 by tumor associated macrophages." (PMID 33953725, 2021). "Conversely, irradiated epidermal cells per se were unable to express CCL17, probably because of radiation-induced skin injury." (PMID 33707490, 2021). "In HCC, tumor-associated neutrophils combined with CCL2 and CCL17 promote the growth, progression, and resistance to sorafenib." (PMID 33568167, 2021). "Ccl2 and Ccl7 control the recruitment of monocytes and neutrophils to the inflamed or tumor tissues, while Ccl17 attracts regulatory T cells." (PMID 34504786, 2021). "Herein, we utilized CCL17 transgenic (TG) mice that were generated in our department, to elucidate key functions of CCL17 in tumor immunity in vivo models." (PMID 33670758, 2021). "Our study indicates that decreases in MDSCs, induced by reductions in CXCL17 as a consequence of CCL17 levels, led to tumor suppression." (PMID 33670758, 2021).
tumor (continued). "The chemokine CCL17 is produced by neutrophils and previous studies have shown that its expression is increased in pro-tumor N2 TANs." (PMID 34853660, 2021). "Subsequently, these TAMs then secreted CCL17, which promoted tumor invasion in vitro and in vivo via activation of mTORC1 signaling." (PMID 33664865, 2021). "In contrast, CCL17 expression was greatly increased in tumor tissues from mice in the GH3+M0+LA group, similar to LDHA and Lamp2 levels, compared with samples from the control and untreated groups." (PMID 33664865, 2021). "MDSCs were significantly decreased in CCL17 TG mice and tremendous recovery of tumor immunity was upregulated by deletion of Tregs in CCL17 TG mice, indicating that tumor immunity was accelerated by the decrease in MDSCs in the absence of Tregs." (PMID 33670758, 2021). "In the present study, we utilized CCL17 TG mice as a relevant in vivo model for AD to explore the mechanism of tumor immunity." (PMID 33670758, 2021). "Chronic hypoxia is also responsible for the recruitment of eosinophils (which participate in neoplastic processes) to a tumor niche dependent on CCL17/TARC expression increase." (PMID 32781743, 2020). "Diminished attraction of Tregs to tumors resulting from reduced Ccl17/22 levels is consistent with improved anti-tumor immunity and attenuated tumor growth." (PMID 31911617, 2020). "Mature DCs can also secrete cytokines to foster T cell response and release chemokines such as CXCL9, CXCL10, CCL3, CCL4, and CCL17 to recruit T cells into the tumor bed." (PMID 33505304, 2020). "Our ability to rescue, in part, Treg recruitment and tumor growth in Siah2−/− mice subjected to treatment with neutralizing antibodies to Ccl17 and Ccl22 further illustrates the independent pathways by which Siah2 controls tumor growth." (PMID 31911617, 2020). "Several other pro-inflammatory targets leading to potentially tumor-toxic effects, such as CCL17, IFNγ, IL1β, and IL6, were increased in tendency." (PMID 32316245, 2020). "In syngeneic mouse tumor models, TANs in tumor-bearing mice secreted CCL17 to induce regulatory T cell (Treg) infiltration into tumor sites, thereby boosting tumor growth." (PMID 32422991, 2020). "It has been shown that recruitment of regulatory CD4+ T cells into tumors via secretion of CCL17 by tumor accumulating neutrophils represent a potent mechanism of impairment of local antitumor immunity." (PMID 32813937, 2020). "In another study, Ang-2 also increased expression of interleukin-10 (IL-10), mannose receptor (MRC-1), and chemokine (C-C motif) ligand 17 (CCL-17) in TEMs, which are three markers for the so-called “pro-tumor M2-like macrophages." (PMID 32085414, 2020). "We next evaluated the expression of Mcp-1, Ccl17 and Rankl mRNA by each tumor 2 weeks after the transplantation of tumor cells." (PMID 31888216, 2019). "Most of the tumor-infiltrating CD4+ cells in gastric MALT lymphoma were shown to be FOXP3+ Tregs, and these Tregs were recruited by tumor cells through the chemokines CCL17 and CCL22, secreted by FOXP3+ Tregs." (PMID 30999581, 2019). "Further, increased expression of CCL17 in DCs and M2-like TAMs within tumors compared to intestinal lamina propria indicates the establishment of a tumor-promoting immunosuppressive environment." (PMID 31681563, 2019). "The number of CCL2+ or CCL17+ TANs is related to tumor size, microvascular infiltration, tumor embedding, tumor differentiation and staging." (PMID 31464625, 2019). "A major pathway in the recruitment of Tregs into the tumor microenvironment is the CCL17/22-CCR4 pathway." (PMID 30979375, 2019). "In the present study, we examined the contribution of 4T1 cell-derived GM-CSF to the tuning of the tumor microenvironment by examining the expression of the Mcp-1, Ccl17 and Rankl gene by 4T1 tumors." (PMID 31888216, 2019). "In the present study, we only found CCL17 expression in a small fraction of tumor cells in 3/35 ALK− ALCL cases." (PMID 31581676, 2019).
tumor (continued). "CD4+ helper T lymphocytes react to CAF secretion of CCL2, CCL5, and CCL17 along with polarizing cytokines IL-1, IL-6, IL-13, and IL-26 by switching from an anti-tumor TH1 response to a pro-tumor TH2 and TH17 response." (PMID 31058816, 2019). "Previous studies have revealed that CCL17/TARC possesses several important effects attributed to tumor growth, such as the proliferation, migration and recruitment of regulatory T-cells." (PMID 30140381, 2018). "In contrast, one of the major sources of CCL17 in the affected skin of patients with ATL is the tumor cell itself." (PMID 29915722, 2018). "Chemokine (C–C motif) ligand 17 (CCL17), also known as thymus and activation-regulated chemokine (TARC), is a chemokine produced by myeloid dendritic cells, endothelial cells, bronchial epithelial cells and several tumor cells." (PMID 28178948, 2017). "In this study, we found that CCL17 was predominantly expressed on cytoplasm of tumor cells through immunochemistry, and high CCL17 expression turned out to be positively correlated with a better prognosis." (PMID 28178948, 2017). "CCL17 expression was predominantly found on the cytoplasm of tumor cells and the intensity of the staining was variable." (PMID 28178948, 2017). "Whereas, the arrival of TANS perpetuates a sustained release of CCL2, GM-CSF, CCL17 which correspond to elevated tumor size, microvascular invasion and inward migratory activity of the macrophages and Tregs." (PMID 28441391, 2017). "Overall, our data suggest that in malignant tissues with increased CCL17/22 secretion, Th2-like Tregs are preferentially attracted to tumor sites, where they display a survival advantage and the ability to inhibit Th1-Th17-Th1/17 effector lineages." (PMID 28723576, 2017). "ROS, and RNS promote genomic instability and mediate angiogenesis by release of VEGF, CCL17 recruiting Treg in the tumour, MMP-9, or Prokinectin -2, and neoplastic cell invasion through the release of soluble factors (Eg-HGF and Oncostatin)." (PMID 28275390, 2017). "Chemokines that work in the favour of recruiting tumour homing cytotoxic T-lymphocytes and macrophages such as GM-CSF, CCL17 and CCL4 were increased specifically in Fe-bLf-Dox treatment." (PMID 27576789, 2016). "In an animal BC model, tumor cells were shown to induce production of chemokine ligands, especially CCL17 and CCL22, at secondary sites, leading to chemotaxis of both tumor and immune cells." (PMID 27990412, 2016). "We did not observe any correlation between CCL17 production and the numbers of mDCs in the tumor tissue; however, we observed a significant positive correlation between the CCL17 levels and the numbers of tumor-infiltrating pDCs (r = 0.91; p < 0.001)." (PMID 25949860, 2015). "M2a macrophages can promote the recruitment of eosinophils and basophils by secreting CCL24 and CCL17, and can promote tumor cell migration." (PMID 26684869, 2015). "The chemoattractant properties of CCR4/CCL22 and CCR4/CCL17 for Treg cells were assessed using the Boyden chamber technique, to elucidate the potential mechanisms of Treg recruitment in tumor microenvironment." (PMID 26020249, 2015). "In patients with ovarian carcinoma, the host response to the tumor has been shown to be inhibited by Foxp3+CCR4+ Tregs recruited to the tumor by CCL17 and CCL22." (PMID 26197455, 2015). "M2-like TAM have high levels of mannose receptor-1 (MRC1/CD206), arginase-1 (Arg1), IL-10 and chemokines CCL22 and CCL17, whereas anti-tumor M1-like TAM express high interferon (IFN)γ and IL-1α/β levels; TNFα marks both M1- and M2-polarized TAM." (PMID 24317954, 2013). "In CRC, KRASG12C/D/V mutations resulted in ROS accumulation, leading to the upregulation of lactate and GM-CSF, thus recruiting macrophages and transforming them into more tumor-supportive tumor-associated macrophages (TAM)-like cells that secreted higher levels of IL-10, CCL17, and TGF-β1." (PMID 40611261, 2025).
tumor (continued). "This current work addresses the tumor-promoting effects of M2-like macrophages-derived CCL17 on the migration, invasion and stemness characteristics of ESCC cells and to thoroughly elucidate the intrinsic molecular mechanisms, aiming to develop promising targets and drugs for ESCC therapies." (PMID 39473097, 2025). "The N2 markers include CCL17, CCL2, Arg, CCL5, and vascular endothelial growth factor (VEGF).The role of transforming growth factor-β (TGF-β) signaling within the tumor microenvironment (TME) has been implicated in the promotion of a pro-tumorigenic neutrophil phenotype (N2)." (PMID 40160822, 2025). "The observed downregulation of Ccl17, which is involved in immune cell trafficking, suggests a diminished inflammatory response that could potentially alter the tumor microenvironment." (PMID 41282050, 2025). "In the RLS40 model, the neutrophil phenotype was associated with the tumor growth rate, where, in aggressively progressed tumors (RLS40High), CCL17 was expressed, while, in mice with controlled tumor growth (RLS40Low), anti-tumor markers were expressed (FAS, ICAM-1, PD-L1)." (PMID 40867260, 2025). "At the same time, in the RLS40 model, DNase treatment resulted in a decrease in the mRNA levels of pro-tumor phenotype markers (Ccl17, Il10) and an increase in the mRNA levels of anti-tumor phenotype markers (Icam1, Tnfa, Vegfr1), as well as cell mobilization genes (Ern1, Stat3)." (PMID 40867260, 2025). "Treg recruitment into the TME is accomplished via CCR4/CCL22 or CCR4/CCL17 pathways after interactions between CCR4+ Tregs and CCL22/CCL17 secreted by TAMs and tumor cells; as such, CCR4+ Tregs abundantly infiltrate the TME and are considered the most immunosuppressive subset of Tregs." (PMID 40649958, 2025). "CCL17 contributes to tumor immunosuppression by recruiting Tregs to the TME." (PMID 40867260, 2025). "When co-culturing CAR T cells with TB32043mb6s2 cells in vitro, a significant secretion of CXCL2, CXCL16 and CCL17 was observed, which are potentially tumour-promoting factors that could hinder therapeutic efficacy in vivo." (PMID 40361460, 2025). "To explore these inquiries, we analyzed public databases to compare the levels of CD137 highly (CD137hi) expressing-IFNγ-producing CD8+ T cells, IL12-producing M1 cells and CCL17-producing M2 in tumor tissues from five different cancer types, depending on the response to anti-PD-1 treatment." (PMID 38254759, 2024). "Sorafenib also mediated the infiltration of tumor-associated neutrophils (TANs) in hepatocellular carcinoma patients and animal models, while TANs further promoted more intratumoral macrophages and T-regulatory (Treg) cells through secreting CCL2 and CCL17." (PMID 38787372, 2024). "CCL17 promotes tumor invasion through the CCL17/CCR4/mTORC1 pathway." (PMID 38716256, 2024). "Together, these results indicate that STAT6 mutant rrDLBCL cells remodel their tumor microenvironment (TME) via the secretion of the chemokine CCL17 to attract CD4+ T-cells, although the subtype of CD4+ T-cells which were recruited were not determined in this study." (PMID 38285120, 2024). "Interestingly, the density of Tregs in the tumor area positively correlated with levels of CCL17 in the secretome of matched tumors (Spearman’s ρ=0.70, p=0.02)." (PMID 39053947, 2024). "However, CCL17-positive cells have only been reported to be distributed within the tumor stroma in the context of HCC." (PMID 38914802, 2024). "We hypothesize that CCL17 exerts a chemotactic function on T cells within the tumor-immune microenvironment, attracting activated CD8+ T cells to the tumor site to elicit antitumor effects." (PMID 39877375, 2024). "Furthermore, a CCL17/22-rich milieu orchestrated by myeloid cells leads to local nTreg chemoattraction, which has been shown to enable tumor immune evasion, prevent autoimmune diabetes and promote donor-specific tolerance." (PMID 37828996, 2023). "M2‐TAMs that secrete CCL17 and IL‐10 have been shown to promote tumor growth." (PMID 35838343, 2023).
tumor (continued). "In LUAD, the high expression of chemokine CCL17 promotes local immune infiltration and anti-tumor immune response, which may contribute to better survival and prognosis of early LUAD patients." (PMID 37187527, 2023). "Here, early production of CCL2 and CXCL1 may help with shaping the initial myeloid cell compartment in cancer-bearing individuals, which promotes tumour development and production of CCL17 and CXCL10 which in turn modulates recruitment of leukocytes." (PMID 35226704, 2022). "CCL17/22 expression was observed in only tumor and myeloid cells." (PMID 35025968, 2022). "Notably, the pathomechanism of metastatic breast cancer involves primary tumor growth in mammary pads, which activates the expression of CCL17 and CCL22 in the lungs." (PMID 36555280, 2022). "In the CT26 tumour model, we identified early levels of CXCL1, CCL2 and CCL17 as having important roles in predicting tumour growth as well as similar pairwise correlations with factors directly correlating with tumour growth and one another, suggesting they played similar roles in this context." (PMID 35226704, 2022). "Indeed, TAMs in the patch stage produce proinflammatory chemokines (e.g., CXCL5, CXCL10), whereas in the tumor stage they produce Th2 chemokines (e.g., CCL17, CCL22)." (PMID 35409404, 2022). "In hepatocellular carcinoma, tumor cells and TAN work together to activate neutrophils in peripheral blood of patients, secrete chemokine CC motif ligand 2 (CCL2) and chemokine CC motif ligand 17 (CCL17), and then promote tumor growth, proliferation, and macrophage growth." (PMID 35965533, 2022). "Depending on the particular EBV+ tumor type, this CCL17 and CCL22 expression could be coming from the tumor cells themselves, infiltrating host immune cells, or a combination of the two." (PMID 35025968, 2022). "Interestingly, high levels of MCP-1 correlate with a higher percentage of Th2 cells compared to Th1 in primary tumor tissue and induce macrophages to secrete Th2, which recruits the chemokines CCL17 and CCL22." (PMID 36286034, 2022). "CCL17 was highly expressed in sporadic regions across the tumor, and in most of these regions the high expression was beyond what cell abundance alone could explain." (PMID 35046414, 2022). "Furthermore, TANs secrete CCL2 and CCL17, which correlate with tumor size, microvascular invasion, extent of tumor differentiation, staging, and poor survival time." (PMID 36613878, 2022). "CCL17 is a ligand for CCR4, which activates CCR4-expressing Th2 cells and regulatory T-cells (Tregs) and suppresses effector cells; KCNE4 may contribute to tumor cell survival through activation of Tregs via increasing CCL17 production." (PMID 35915077, 2022). "In both cases, tumor-produced chemokines CCL17 and CCL22 trigger Treg migration by activating the CCR4 chemokine receptor, and, in both cases, the viral protein LMP1 may be central to this process." (PMID 35025968, 2022). "In contrast, treatment with AZD2098 markedly reduced the CCL17-induced tumor burden." (PMID 33664865, 2021). "Moreover, CCL17 released from M2-like TAMs enhances tumor invasion of PAs via the CCL17/CCR4/mTORC1 axis." (PMID 33664865, 2021). "CCL17 has at least two distinct mechanisms to regulate tumor development." (PMID 33670758, 2021). "Interestingly, tumor formation in CCL17 TG mice was markedly reduced compared with WT mice after depletion of Tregs." (PMID 33670758, 2021). "Moreover, evidence surfaced demonstrating that CCL2 and CCL17 expression in TANs was correlated with tumor progression and prognosis in patients with HCC." (PMID 34200529, 2021). "Tumor formation by EL4 cells in CCL17 TG mice was also enhanced compared with WT mice." (PMID 33670758, 2021). "As CCL17 is overexpressed in AD, it is interesting to focus on the role of CCL17 in tumor immunity." (PMID 33670758, 2021).